AKT3 (AKT serine/threonine kinase 3)
Diseases named in the same sentence as AKT3 in open-access papers (continued):
Sharing a sentence is not in itself a finding about the gene and the disease.
ovarian carcinoma (continued). "Collectively, these results indicate that AKT2 and AKT3 promoted ovarian cancer progression, probably by enhancing cancerous glycolytic metabolism." (PMID 26512921, 2015). "It has previously been found that over-expression of AKT3 is a critical factor that correlates with cell proliferation in ovarian cancer." (PMID 24362839, 2014). "In EOC cells, the AKT3 expression is negatively regulated by downregulated miR-29b, thus inducing the rate-limiting glycolytic genes hexokinase 2 and pyruvate kinase M2 and increasing the Warburg effect and ovarian cancer progression." (PMID 37998329, 2023). "This hypothesis was also supported by the positive correlation between AKT3 and BRCA1 IHC expression, a biomarker which has already been associated with stemness-like features and resistance in ovarian cancer." (PMID 35053468, 2022). "In ovarian cancer, the overexpression of AKT3 could promote the proliferation and migration of cancer cells." (PMID 34983559, 2022). "Moreover, miR-29b, which is dysregulated in obesity and DM, can also affect the Warburg effect via downregulating AKT2 and AKT3 in ovarian cancer cells." (PMID 34751020, 2022). "Other transcripts included AKT3 and GSK3β, coding for the variable 3 of protein kinase b and for Glycogen synthase kinase 3 beta, respectively; both factors induce cell proliferation and migration in ovarian carcinoma cells." (PMID 35562985, 2022). "Since miR-150 can upregulate glycolysis via targeting AKT3, it may directly reduce the Warburg effect and resistance in ovarian cancer cells." (PMID 34751020, 2022). "Interestingly, a previous study reported AKT3 as a target of miR-654-3p, and the miR-654-3p/AKT3 axis was closely involved in the proliferation and invasion of ovarian cancer cells." (PMID 34103010, 2021). "In this paper, the reduced proliferation was seen in two cell lines that exhibited the highest levels of Akt3 expression, suggesting that Akt3 ablation may be effective in a subset of ovarian cancers." (PMID 27533079, 2016). "Next, we determined the effects of AKT2 and AKT3 on in vitro ovarian cancer cell proliferation." (PMID 26512921, 2015). "However, miR-29b negatively regulated both AKT2 and AKT3 expression in both of the selected ovarian cancer cell lines." (PMID 26512921, 2015). "Briefly, ovarian cancer cells were transfected with miR-29b or control mimics in addition to a luciferase construct containing either the wild-type AKT2/AKT3 3′UTR or a mutant AKT2/AKT3 3′UTR." (PMID 26512921, 2015). "The Glu17Lys mutation seen in the binding site of AKT3 in kidney cancer was also found in the pleckstrin homology domain of AKT1 in breast, colorectal and ovarian cancers, and results in the activation of AKT1, followed by downstream signaling and cell transformation." (PMID 24362839, 2014). "We have shown that AKT3 is upregulated in 20% of ovarian cancers." (PMID 21869924, 2011). "However, since it was selected both by Net-Cox and fastcox, a possible significant relation between AKT3 and ovarian cancer could be inferred as indeed confirmed by literature." (PMID 27378931, 2016). "DCN (Decorin), AKT3 (AKT Serine/Threonine Kinase 3), and TIMP2 (tissue inhibitor of metalloproteinases 2) are the other novel candidate target genes for miR-182 involved in the regulation of ovarian cancer biological processes." (PMID 34721577, 2021). "The constitutive activation in ovarian cancer is a result of amplification of pathway components like PI3K subunits (p110), AKT isoforms (AKT1, AKT2, or AKT3), or members of the mTOR complexes (RICTOR, RAPTOR)." (PMID 27090655, 2016). "Intriguingly, the ovarian cancer tissues that exhibited lower miR-29b expression also showed higher levels of AKT2 and AKT3 compared to their counterparts that exhibited higher miR-29b expression." (PMID 26512921, 2015).
ovarian carcinoma (continued). "While p−AKT (Ser473) can, to some extent, reflect the general pathway activity, the three AKT isoforms (AKT1, AKT2 and AKT3) are not functionally equivalent in ovarian cancer." (PMID 41458598, 2025). "We have found that EMX2OS, which has been expressed in ovarian cancer, may inhibit tumor development and development by acting on PD-L1 (procedural cell death protein 1) through the EMX2OS/miR-654/AKT3 axis." (PMID 35662687, 2022). "Interestingly we found that AKT3 and PIK3C2B were 32% and 27% significantly higher, respectively, in ovarian cancer datasets." (PMID 35205706, 2022). "Moreover, our approach selected new genes, such as AKT3 and RB1, which are also related to ovarian cancer." (PMID 27378931, 2016). "We then examined miR-29b and its latent downstream targets, AKT2 and AKT3 in 30 human ovarian cancer tissues and 30 matched normal ovarian tissues as negative controls." (PMID 26512921, 2015). "The MTT assay results showed that over-expression of AKT2 and AKT3 enhanced cellular proliferation in the A2780 and SKOV3 ovarian cancer cell lines, while simultaneous over-expression of miR-29b and AKT2/3 led to no statistically significant change in cellular proliferation." (PMID 26512921, 2015).
prostate carcinoma (41 papers, 2006 to 2025). A carcinoma that arises from epithelial cells of the prostate gland. "The genetic variant rs10157763 in AKT3 has been previously associated with aggressive prostate carcinoma and renal cell carcinoma." (PMID 27193124, 2016). "Our findings demonstrate AKT3 as a potential therapeutic target and diagnostic tool in advanced neuroendocrine prostate cancer and a new mRNA–miRNA interaction with a potential role in neuroendocrine differentiation of prostate cancer." (PMID 33540707, 2021). "Down-regulation of TSC1 and TSC2 as well as up-regulation of B-Raf caused by elevation of AKT3 may therefore contribute to the increase of cellular proliferation and provide growth advantage for prostate cancer cells." (PMID 26318033, 2015). "Furthermore, a treatment with a miR-16-5p mimic demonstrated that this miRNA could induce apoptosis and reduce the viability of prostate cancer cells by targeting a key target gene associated with carcinogenesis, i.e., AKT3." (PMID 41465187, 2025). "Investigations have revealed that activation of PPARγ in prostate cancer cells increased mitochondrial biogenesis and ATP levels by upregulating AKT3, which enhanced the nuclear localization of PGC1α." (PMID 39791746, 2025). "MiR-29b inhibits cell proliferation and invasion, and enhances cell apoptosis via targeting of AKT3 in prostate cancer." (PMID 37770840, 2023). "PPARG overexpression also induces the upregulation of AKT3 and triggered mitochondrial ATP synthesis, contributing to prostate cancer progression with elevated energy supplies." (PMID 37932808, 2023). "In human prostate cancer, miR-511-3p acts as a tumor suppressor by targeting AKT3 to inhibit tumor growth in vivo and in vitro." (PMID 34989314, 2022). "There is a study showing that AKT3 can promote prostate cancer cell proliferation by regulating Akt, B-Raf, and TSC1/TSC2." (PMID 36593867, 2022). "To analyze if AKT3 plays a role in neuroendocrine differentiation of prostate carcinoma, we validated AKT3 expression in NE-like LNCaP cells compared to undifferentiated LNCaP cells in four independent differentiations by qRT-PCR." (PMID 33540707, 2021). "Taken together, our results suggest that a subpopulation of neuroendocrine cells express AKT3 in advanced prostate carcinoma." (PMID 33540707, 2021). "To analyze AKT3 protein localization in neuroendocrine differentiated PCa, we collected tissue samples from patients with prostate cancer, performed HE staining and determined the Gleason Score." (PMID 33540707, 2021). "In human specimens, we found Akt1 and Akt2 positively correlated, whereas Akt3 inversely correlated, with the overall survival of prostate cancer patients." (PMID 34591413, 2021). "Activating mutations in AKT1–3 are relatively rare in prostate cancer, while gene amplification has been observed in up to 4.5% (AKT1), 2% (AKT2), and 4.7% (AKT3) of prostate cancer cases, respectively." (PMID 33105713, 2020). "The analysis of large-scale genomic studies of the TCGA and other prostate cancer databases provided evidence that in the large majority of patients CHD1 loss and PTEN deletion (as well as AKT1, AKT2, AKT3, and PIK3CA gene alterations) were mutually exclusive." (PMID 31366128, 2019). "The signature molecules associated with GCR signaling pathway in prostate cancer include heat shock proteins (HSP), Keratins (KRT), SUMO1, AKT3, and others." (PMID 30972102, 2019). "AKT3 mRNA and protein expression is also increased in prostate tumours, and overexpression of AKT3 promotes cell proliferation in a range of prostate cancer cell lines." (PMID 28082369, 2017). "Plasmid overexpression of AKT3 promoted cell proliferation of LNCaP, PC-3, DU-145, and CA-HPV-10 human prostate cancer (PCa) cells, while knockdown of AKT3 by siRNA reduced cell proliferation." (PMID 26318033, 2015).
prostate carcinoma (continued). "Our observation showed that mRNA and protein expression of AKT3 was higher in primary prostate tumors and that elevation of AKT3 promotes growth of prostate cancer cells." (PMID 26318033, 2015). "In PC-3 and DU-145 cells, the abundance and enzymatic activity of AKT3 was approximately 20–60-fold higher than that in the LNCaP prostate cancer cells." (PMID 26318033, 2015). "The mRNA expression of AKT1, AKT2, and AKT3 are detected in both normal and prostate cancer tissues." (PMID 26318033, 2015). "Our observation indicated that overexpression of AKT3 augmented protein abundance of B-Raf, which promotes the proliferation of prostate cancer cells." (PMID 26318033, 2015). "Transient knockdown of AKT1, AKT2, or AKT3 using siRNA suppresses the proliferation of prostate cancer cells both in vitro and in vivo." (PMID 26318033, 2015). "In conclusion, our observations suggested that elevation of AKT3 promotes the proliferation of prostate cancers cells through regulation of Akt, B-Raf, & TSC1/TSC2." (PMID 26318033, 2015). "We discovered that the elevation of AKT3 promoted the proliferation of different prostate cancer cell lines via induction of AKT phosphorylation and B-Raf as well as the reduction of TSC1 and TSC2." (PMID 26318033, 2015). "Akt3 enzymatic activity was approximately 20-60-fold higher in AR-negative PC-3 and DU-145 cells compared to the AR-positive LNCaP prostate cancer cells." (PMID 22347457, 2012). "It is already well described that AKT3 is expressed in healthy prostate and prostate carcinoma, whereat Nakatani and colleagues gave a first hint that AKT3 could play a bigger role in advanced prostate cancer." (PMID 33540707, 2021). "Notably, Akt3 mRNA levels are comparable with Akt2 levels (TCGA) in prostate cancer, suggesting a tight post-transcriptional regulation to limit its protein levels in tumors." (PMID 34591413, 2021). "Our results indicate that AKT3 may play a role in NE-like LNCaP cells as well as in neuroendocrine differentiated prostate cancer." (PMID 33540707, 2021). "For example, a prostate cancer study found that AKT3 overexpression could lead to increased resistance of differentiated neuroendocrine tumor cells to androgen therapy." (PMID 34882061, 2021). "AKT1, AKT2, and AKT3 activating mutations are rare in prostate cancer (≤0.9%, predominantly in AKT1 at E17K), whereas AKT1, AKT2, and AKT3 high-level gene amplification that can increase AKT activity is more common, particularly in advanced disease (up to 4.5%, 2%, and 4.7% incidence respectively)." (PMID 32630372, 2020). "Many researchers have shown that PPP1R3C, PPKAR2B and AKT3 may play important roles in cervical cancer, cardiovascular events and prostate cancer." (PMID 33176720, 2020). "AZD5363, a Akt3 inhibitor, inhibits proliferation in prostate cancer, which suggests it could also have therapeutic effects in in FPA." (PMID 31655798, 2019). "AZD5363 is one of Akt3 inhibitors and an apoptosis promoter in prostate cancer." (PMID 31655798, 2019). "However, in clinical prostate cancer samples, Akt1 and -2 were reportedly localized both in cytoplasm and nucleus, whereas Akt3 was observed in cytoplasm." (PMID 28483982, 2017). "The significant elevation of AKT3 proteins in prostate tumors may allow the AKT3 to be a potential therapeutic target for prostate cancer." (PMID 26318033, 2015). "In contrast, Akt-3 expression correlated with extracapsular invasion and hormone-refractory disease progression, suggesting that Akt-3 is involved in the invasion potential of prostate cancer cells, and may therefore play a role in later stages of the disease." (PMID 16721361, 2006). "We hypothesize that AKT3 may play important role in regulating prostate cancer cell proliferation." (PMID 26318033, 2015).
prostate carcinoma (continued). "AKT3 protein level was examined by western blot analysis in two AR-positive, LNCaP and 22Rv1, as well as two AR-negative, DU145 and PC3, prostate cancer cell lines to confirm a correlation between AR signaling and AKT3 expression." (PMID 33540707, 2021). "The POU1F1-derived tumors have 499 exclusive proteins that participate in events such as Platinum drug resistance (AKT3, BCL2 and GSTT2) and Prostate cancer (FGFR1, IGF1R and PDGFD) among others." (PMID 33261069, 2020). "Our study showed that PI3K, Akt3, and PDPK1 form a cFFL; all involving in prostate cancer formation." (PMID 25707690, 2015). "Overexpression of AKT3 increased 10–25% of cellular proliferation in PC-3, DU-145, CA-HPV-10, and LNCaP human prostate cancer cells." (PMID 26318033, 2015). "Our observation suggested that overexpression of AKT3 in prostate cancer cell lines dramatically enhanced the phosphorylation of AKT on both Thr308 and Ser473, indicating that the activity of AKT3 increased significantly." (PMID 26318033, 2015). "Knockdown of AKT3 with siRNA decreased 5–30% of cellular proliferation in PC-3, DU-145, and CA-HPV-10 prostate cancer cells." (PMID 26318033, 2015). "Because E2F3 interact with ARNT, we can infer the interactions between two dependent genes AKT3 and CHUK and map to their gene products, protein PKB and IKK in prostate cancer pathway." (PMID 20025723, 2009). "The AKT3 targeting strategy is specifically effective for ER-negative, androgen receptor (AR)-negative breast or prostate cancer cells." (PMID 33861751, 2021). "Up-regulation of AKT3 mRNA and protein expression levels occurs in oestrogen receptor-negative breast cancers and androgen receptor-independent prostate cancer cells, and phosphorylated AKT3Ser473 expression is increased in metastatic melanomas." (PMID 28082369, 2017). "As overexpression of AKT3 decreased protein level of TSC1 and TSC2, we hypothesized that knockdown of TSC1 or TSC2 will enhance proliferation of prostate cancer cells." (PMID 26318033, 2015). "Our observation suggested that AKT3 can regulate the proliferation of prostate cancer cells independent of AKT1 or AKT2." (PMID 26318033, 2015). "For example, Akt-3 is not expressed in androgen receptor positive prostate cell lines and no constitutive activation of Akt-2 has been observed in prostate cancer cell lines while Akt-1 is constitutively activated in most prostate cancer cell lines." (PMID 16721361, 2006). "In addition, knockdown of AKT1 or AKT2, but not AKT3, facilitated cell migration via an increase in activity of integrin β1 in prostate cancer cells." (PMID 26741489, 2016). "As cDNA overexpression of AKT3 and siRNA knockdown of AKT3 showed opposite effects on phospho-AKT S473, phospho-AKT T308, B-Raf, TSC1 and TSC2, these proteins may play essential roles in the proliferation regulation of AKT3 in prostate cancer cells." (PMID 26318033, 2015). "However, the clinical significance of AKT3 is not clear and how AKT3 may promote prostate cancer cell proliferation is not understood." (PMID 26318033, 2015). "In sum, our data indicate that PTEN alters AKT isoform dependency such that metastatic prostate cancer progression likely involves substrates preferred by AKT2 and/or AKT3, but not by AKT1." (PMID 37875657, 2024).
gastric cancer (38 papers, 2017 to 2025). A primary or metastatic malignant neoplasm involving the stomach. "CDH1-deficient gastric cancers exhibit high AKT serine/threonine kinase 3 (AKT3) expression, but specific drugs against this AKT isoform are not available." (PMID 35406381, 2022). "Among the CGCs in module A, we identified AKT3, which is an oncogene that is associated with gastric cancer cell proliferation." (PMID 32127608, 2020). "Bioinformatics analysis indicates that there is a strong correlation between the loss of CDH1 and an increased expression of AKT3 in gastric cancer." (PMID 31540244, 2019). "In particular, hsa_circ_0000199, originating from exons 8–11 of the AKT3 gene, is overexpressed in cisplatin-resistant gastric cancer." (PMID 37998329, 2023). "LINC00565 also targets the miR‐665/AKT3 axis in gastric cancer, enhances proliferation, and prevents apoptosis." (PMID 36129020, 2023). "To further understand the activity of AKT3 in gastric cancer and develop strategies to preferentially target this isoform, we identified AKT3-associated genes in the TCGA and GEO datasets." (PMID 35406381, 2022). "Reactome analysis identified an enrichment of extracellular matrix remodelling genes in AKT3-high gastric cancers." (PMID 35406381, 2022). "Another study has revealed the role of miR-582-5p as a tumor-suppressor in gastric cancer cell growth via targeting AKT3, suggesting it as a target for treatment as well as diagnosis of gastric cancer." (PMID 32992741, 2020). "circ-AKT3 promoted cisplatin resistance in gastric cancer by suppressing miR-198 and upregulating PIK3R1." (PMID 32855967, 2020). "In gastric cancer, miR-582-5p has been verified to restrain cell growth by down-regulating the expression of AKT3." (PMID 31170211, 2019). "Another circRNA generated from AKT3 (hsa_circ_0000199) was recently reported to be upregulated in gastric cancer." (PMID 31470874, 2019). "Together, the resulted showed that UCA1 affected malignant progression of gastric cancer cells partly through p-AKT3 and p-mTOR in the PI3K-Akt-mTOR signaling pathway." (PMID 29212166, 2017). "Circular RNA AKT3 could regulate drug resistance in gastric cancer (GC) cells via inhibition of miR-198 and upregulation of PIK3R1." (PMID 37608665, 2024). "miR-582-5p can target AKT3 to inhibit proliferation of gastric cancer cells." (PMID 39464718, 2024). "Furthermore, the introduction of miR-29b molecules into breast or stomach cancer cells reduced tumor growth in vitro and in vivo (in a mouse model), by influencing the Akt3 and KDM2A pathways." (PMID 35269947, 2022). "CHI3L1 promotes AKT3 signal during intervertebral disc degeneration and gastric cancer development." (PMID 36615523, 2022). "Circular RNA AKT3 acts as the sponge of miR-198 and promotes gastric cancer cell proliferation." (PMID 34675978, 2021). "Combining experimental results with bioinformatics analysis, we speculate that miR‐195 targets AKT3 to induce apoptosis in gastric cancer cells." (PMID 31515938, 2019). "Moreover, overexpression of miR‐195 promoted apoptosis in gastric cancer cells by targeting AKT3, suggesting miR‐195 acted as a tumour suppressor gene in the development of gastric cancer." (PMID 31515938, 2019). "Therefore, we postulate that the indirect inhibition of AKT3 via DDR2 could be a novel chemopreventative and chemotherapeutic approach for the treatment of E-cadherin-deficient breast and gastric cancers." (PMID 35406381, 2022). "In gastric cancer, NR2F1-AS1 acts as an EMT-inducing lncRNA that enhances cell motility via the miR-29a/VAMP7 axis, activation of AKT3 through miR-190a/PHLDB2, SPI1-mediated transcriptional upregulation of ST8SIA1, and miR-493-5p/MAP3K2 signaling." (PMID 40828427, 2025). "In gastric cancer, NR2F1-AS1 enhances cell growth through various axes, including miR-29a/VAMP7, miR-190a/PHLDB2/AKT3, SPI1/ST8SIA1, and miR-493-5p/MAP3K2." (PMID 40828427, 2025).